DNMT1 (DNA methyltransferase 1)
Diseases named in the same sentence as DNMT1 in open-access papers (continued):
Sharing a sentence is not in itself a finding about the gene and the disease.
cancer (continued). "A potential candidate methyltansferase is DNMT1, which has been widely implicated in the malignant transformation of various cancers." (PMID 26848521, 2016). "In particular, DNMT1 is frequently overexpressed in cancers and contributes significantly to cancer-associated epigenetic silencing of tumor suppressor genes." (PMID 26848521, 2016). "Altered DNA methylation is a common hallmark of cancer, and 200, 590, and 320 somatic mutations in DNMT1, DNMT3A, and DNMT3B, respectively, have been reported in the catalog of somatic mutations in cancers (COSMIC)." (PMID 25815005, 2015). "Exposure of various cancer cell lines to 5-aza-2-deoxycytidine causes radiosensitization accompanied by inhibition and downregulation of DNMT1 and DNMT317, 56; therefore, further research into the development of specific inhibitors of DNMT3B is required." (PMID 26667181, 2015). "Dysregulation of DNMT1 is implicated in a variety of diseases 6, and aberrant methylation contributes to the pathogenesis of human cancers." (PMID 25598321, 2015). "Another interesting result obtained in our study was the increased expression of DNMT1, the enzyme that methylates promoters of tumor suppressor genes in cancer cells, in NSCLC with KRAS mutations." (PMID 25222473, 2014). "Similar results were observed using methylation-specific PCR, and BRCA1-mutated cancer specimens were classified into unmethylated and methylated groups for comparison of the protein expression of DNMT1." (PMID 24502362, 2014). "DNMT1 is an enzyme involved in the regulation of methylated cytosine residues, and its aberrant methylation is associated with cancer development." (PMID 25333365, 2014). "Cellular DNA methylation is orchestrated by three distinct DNA methyltransferases, DNMT1, DNMT3a and DNMT3b, and aberrant expression of these DNMTs has been causally linked to atypical DNA methylation levels in human cancers." (PMID 24252647, 2013). "Both PRC1 and PRC2 proteins interact with DNMT1 and DNMT3b, establishing a potential key role for these proteins in catalyzing methylation-associated transcriptional silencing of target genes in cancer cells." (PMID 24216997, 2013). "In cancer cells loss of Dnmtase activity and suppression of Dnmt1 and Dnmt3b lead to passive loss of global hypomethylation during rapid proliferation." (PMID 22905112, 2012). "Therefore, we conclude that loss of DNA methylation caused by degradation of UHRF1 and/or DNMT1 causes cancer cells to senesce in vivo." (PMID 40595593, 2025). "As cancer remains the second leading cause of death worldwide, and chemotherapy is commonly applied, despite a vast number of serious side effects, novel therapeutic possibilities, such as DNMT1 inhibitors, must be further explored." (PMID 39595939, 2024). "Therefore, our DNMT1 knockdown cell line is a highly suitable model to study if the loss in methylation as observed in cancer can induce mutations or genomic instability." (PMID 37106015, 2023). "DNMT1 dysregulation causes human diseases, such as cancer and various genetic disorders." (PMID 37386587, 2023). "In addition, the deficiency of normal DNMT1 function defects the response of cancer cells to decitabine, which demonstrates that DNMT1 has the potential to be a marker to predict the sensitivity of decitabine." (PMID 35838271, 2022). "Therefore, the aberrant DNA methylation pattern is known as the hallmark of cancer epigenetics characterized by DNMT1, also known as the maintenance methyltransferase." (PMID 35898303, 2022). "PPARγ–DNMT1 co-expression is significantly associated with several cancers." (PMID 34439147, 2021). "In addition, NF-κB has also been associated with the upregulation of DNMT1 in studies that investigated the inflammatory pathway in cancer." (PMID 34421366, 2021).
cancer (continued). "Considering that a DNMT1 deficiency was reported to cause increased genome instability in the APCMin/+ intestinal epithelia, early passage DNMT1 mutations and the functional loss of DNMT1 could lead to the accumulation of other mutations in cancer cells." (PMID 33107222, 2021). "Additionally, upregulated DNMT1 is shown to be necessary for maintaining cancer stemness and is associated with poor clinical outcome of cancers." (PMID 34957104, 2021). "Moreover, both PPARγ and DNMT1 are reported to be enriched with mutations in various cancer types (n = 28)." (PMID 34439147, 2021). "The DNMT1 SNP used, rs2228612, was identified as a cancer risk factor in a meta-analysis." (PMID 34206082, 2021). "The genetic alterations including DNMT1 mutations, and changes in methylation status or gene expression in cancer cells could be one of the potential mechanisms of developing resistance to temsirolimus." (PMID 33107222, 2021). "Mutation of DNMT1 also cause alterations in the genome-wide DNA methylation patterns in colorectal cancer patients, however none of the patients with neurological disorders were shown to develop cancer." (PMID 31091831, 2019). "DNMT1 is overexpressed and caused inhibition of tumor suppressor genes in human cancer." (PMID 31217782, 2019). "However, the actual impact of DNA methylation in somatic cells has proven difficult to study, mainly due to the fact that loss of DNMT1 in mouse models and human cancer cells leads to cell death." (PMID 31320637, 2019). "Here, we report that HIF-2α up-regulates the expression of CD70, a cancer-related surface antigen that improves anchorage-independent growth in cancer cells and is associated with poor clinical prognosis, which can be induced via epigenetic modifications mediated by DNMT1." (PMID 29721188, 2018). "Indeed, we have first revealed DNMT1 up-regulation in most cancer-associated fibroblasts relative to their corresponding adjacent normal fibroblasts." (PMID 29416775, 2018). "The DNMT1 rs2228612 (A/G) GG genotype may be associated with increased risk of cancer compared with the AA + AG genotype." (PMID 28473984, 2017). "However, previous individual studies about the association between DNMT1 polymorphisms and cancer risk were not only limited but also inconclusive." (PMID 28473984, 2017). "Thus, enhancing promoter methylation such as activating DNA methyltransferase 1 (DNMT1) has been implicated in the pathogenesis and progression of human cancers." (PMID 28427182, 2017). "For the associations of DNMT1 rs16999593 (T/C), rs2228611 (G/A), and rs2228612 (A/G) with cancer risk, rs2228612 (A/G) showed publication bias (GG versus AA; G allele versus A allele) and rs16999593 (T/C) showed publication bias in the comparison with the recessive model." (PMID 28473984, 2017). "A possible mechanism of higher expression of DNMT1 in TNBC might be association of TNBC with cancer stem cells." (PMID 27071379, 2016). "The association between DNMT and cancer is based on several observations that correlate the elevated DNMT expression and activity with occurence in several cancer types, wherein DNMT1 overexpression may lead to malignant transformation." (PMID 26317501, 2015). "DNMT1 is closely associated with various cancers; it is a key regulator in DNA hypermethylation." (PMID 26099202, 2015). "Variants in other DNMTs (i.e. DNMT3L, DNMT1) have been associated with human cancers." (PMID 21347319, 2011). "Interestingly, recent studies have associated DNMT1 with methylation of unmethylated human CpG islands in cancer cells." (PMID 20119531, 2009). "Clinically, DNMT1 expression was inversely correlated with miR-34a-5p expression, whereas a positive correlation was noted between DNMT1 and FoxM1 expression levels, and high DNMT1 levels, low miR-34a-5p levels, and high FoxM1 levels were associated with cancer recurrence." (PMID 40050970, 2025). "Therefore, DNMT1 might be implicated in the occurrence, development, and prognosis of multiple types of cancer." (PMID 28473984, 2017).
cancer (continued). "In addition, only in the subgroup of sequencing, DNMT1 rs16999593 (T/C) were constantly associated with increased cancer risk in all compared genetic models, indicating that different genotype detecting methods might influence the results." (PMID 28473984, 2017). "DNMT1 is located on human chromosome 19p13.2 and encodes a protein comprising 1632 amino acids, which may be implicated in occurrence progression and prognosis of the cancer." (PMID 28473984, 2017). "Therefore, inhibition of DNMT1 may be an important mechanism underlying the THL-mediated suppression of the CSC population in cancer cells." (PMID 27525019, 2016). "This issue raises concerns about the risk:benefit ratio with DNMT1 inhibitor use in human disease, which may be justifiable in cancer treatment, as currently permitted, but may be more difficult to justify in less life-threatening disorders involving epigenetic changes." (PMID 25806086, 2015). "Thus, in cancer a deregulation of CTCF-PARP-1 poly(ADP-ribosyl)ation levels may cause the activation of Dnmt1 and the local hypermethylation of the Rb promoter." (PMID 21663659, 2011). "Our findings identify endothelial Dnmt1 as a key regulator of vascular-mediated anti-tumor immunity, providing a rationale for integrating epigenetic modulation of the vasculature with cancer immunotherapy regimens." (PMID 42156591, 2026). "Curcumin, in particular, inhibits DNMT1 activity, fostering hypomethylation and downregulating DNMT1 mRNA in cancer cell studies." (PMID 40663150, 2025). "This study focuses on three critical proteins, DNMT1, Dicer, and PD-1, which play pivotal roles in various signaling pathways and biological processes, making them significant targets for cancer therapeutics." (PMID 40034825, 2025). "Recent empirical evidence indicated the role of the ncRNA/DNMT1 axis in advancing malignant tumours." (PMID 40387409, 2025). "DNMT1, for example, is involved in the DNA methylation pathway and targeted by decitabine, which is used clinically to treat other types of cancer." (PMID 41375077, 2025). "Firstly, CGA can significantly affect the level of DNA methylation, and it shows a broad application prospect in cancer therapy by inhibiting DNA methyltransferases (DNMT), especially DNMT1." (PMID 40727248, 2025). "Several recent studies have elucidated the intricate relationship between epigenetic machinery, specifically DNMT1, and the expression of ncRNAs in the context of cancer." (PMID 40387409, 2025). "Research shows that targeting DNMT1 can reverse the hypermethylation of these promoter regions, potentially restoring the expression of tumor suppressor genes and inhibiting cancer progression." (PMID 40387566, 2025). "Drugs that inhibit DNMT1 or HDACs are already being explored in cancer therapy, but they show promise in treating chronic inflammatory diseases as well." (PMID 41226277, 2025). "In PDX primary to liver metastasis trajectory, we also found a dramatic switch between Tet2 and Dnmt1 at the earlier time points, two enzymes with opposing functions in DNA methylation, which is known to be aberrant in cancer." (PMID 39748426, 2025). "Multiple studies have demonstrated that ncRNAs exhibit the ability to directly interact with DNMT1, resulting in alterations within the cancer cell's epigenome." (PMID 40387409, 2025). "Given its capacity to confer treatment resistance as well, further in-depth investigations into DNMT1 are both necessary and justified to explore potential therapeutic strategies for more effectively managing and combating various cancers." (PMID 40675967, 2025). "Multiple ncRNA/DNMT1 axis regulators have been formulated as potential interventions in cancer therapy." (PMID 40387409, 2025). "DNMT-1, a key enzyme involved in DNA methylation, plays a crucial role in maintaining the epigenetic landscape of cancer cells, contributing to tumor progression and silencing tumor suppressor genes." (PMID 40034825, 2025).
cancer (continued). "Over the last two decades, an increasing body of evidence has established the involvement of DNA methyltransferase 1 (DNMT1) in various aspects of cancer development, including tumorigenesis, aggressiveness and treatment response." (PMID 40387409, 2025). "To this end, we activated L1TD1 expression by inducing DNA hypomethylation via deletion of DNMT1 in the nearly haploid human cancer cell line HAP1." (PMID 40112032, 2025). "To answer this question, we analyzed the pan-cancer de novo assembly transcriptome, which reported deregulated transcripts after the dual inhibition of DNMT1 and HDACs in cancer cell lines and the distance of the nearest repetitive element from the TSS." (PMID 40498028, 2025). "Having established that the depletion of UHRF1 and/or DNMT1 triggers senescence in cancer cells in vitro, we next sought to test if this also occurred in an in vivo setting." (PMID 40595593, 2025). "In many types of cancer, aberrant methylation is frequently accompanied by DNMT1 overexpression, which is fueled by signaling cascades controlled by cancer cells." (PMID 40581650, 2025). "In this review, we provide a comprehensive overview of the interaction between DNMT1 and ncRNAs in cancer pathogenesis." (PMID 40387409, 2025). "The primary focus was on enzymes like 5α-reductase and CYP17, which are central to androgen biosynthesis, as well as on cancer-related proteins such as DNA methyltransferase 1 (DNMT1), Dicer, programmed death-1 (PD-1), and programmed death ligand-1 (PD-L1)." (PMID 40034825, 2025). "UHRF1, a key DNMT1 cofactor often overexpressed in cancers, binds hemimethylated CpG sites and recruits DNMT1 to maintain DNA methylation." (PMID 41204384, 2025). "Evidence has shown that the PI3K/AKT pathway mediates epigenetic regulation in cancer through DNMT1 and DNMT3B stabilization and upregulation in cancers such as glioblastoma and leukemia." (PMID 40427627, 2025). "Lastly, it is also important to acknowledge the context-dependent nature of DNMT1 in cancer biology." (PMID 41381440, 2025). "The effectiveness of 5-AzaC and 5-AzaDC against cancer cells is primarily supposed to be based on the cytotoxicity of the adducts formed between these analogs and DNMT1 in the DNA strand." (PMID 41551874, 2025). "For example, the activation of the MAPK/ERK pathway in human cancer cells has been demonstrated to enhance the expression of DNMT1, a key enzyme in maintaining DNA methylation patterns during replication." (PMID 39996888, 2025). "This complexity highlights the profound influence of epigenetic regulation in cancer biology, with DNMT1 as a central figure in the maintenance of oncogenic states." (PMID 40034825, 2025). "The IHC results showed that the nucleus of cancer cells overexpressed DNMT1 while adjacent tissue cells showed significant lower expression." (PMID 40317882, 2025). "Depletion of DNMT1 was shown to markedly reduce the growth inhibition, cytoxicity and abrogated the cell cycle arrest, DNA damage and apoptosis in cancer cells." (PMID 40011240, 2025). "In this manner, exploring the function of DNMT1 in cancer presents a valuable opportunity to increase our understanding of tumour biology and to identify potential therapeutic targets." (PMID 40387409, 2025). "Building on reports that NEAT1 interacts with DNMT1 in cancer models, we investigated this axis in LN." (PMID 41457558, 2025). "miR-148a targets DNMT1 and reduces its levels in cancer, whereas miR-29 Family is known as a repressor of DNMT3A and DNMT3B expression by directly targeting their mRNAs." (PMID 39996888, 2025). "The primary function of DNMT1 is maintaining CpG methylation status during cell division (maintaining the cancer stem cell status), while DNMT3A and DNMT3B are predominantly involved in de novo methylation." (PMID 40507223, 2025).
cancer (continued). "Preclinical studies suggest that DNMT1 inhibition can upregulate PD-L1 expression, cancer-testis antigens (CTAs), and other TAAs, presenting promising targets for cancer immunotherapy." (PMID 39996888, 2025). "We report here that L1TD1 deletion in DNMT1-deficient cells led to reduced cell viability and increased apoptosis in HAP1 cancer cells." (PMID 40112032, 2025). "Specifically, it has been demonstrated that DNA methyltransferases 1 (DNMT1), 3A, and 3B are significant de novo and maintenance methyltransferases in cancer." (PMID 40167762, 2025). "Decitabine induces DNA hypomethylation by directly incorporating into replicating DNA and inhibiting DNA methylation by DNMT1 depletion, leading to the reactivation of silenced genes and differentiation in cancer cells." (PMID 40761187, 2025). "Collectively, these studies show that DNMT1-dependent DNA methylation inheritance is a ubiquitin-regulated process that is partially reliant on UHRF1 and suggest a disrupted UHRF1-DNMT1 ubiquitin signaling axis contributes to PMD formation in cancers." (PMID 39607687, 2024). "Unexpectedly, we observed a nearly complete hypomethylation pattern, remodeled by DNMT1 silencing, alongside effective suppression of cancer." (PMID 38755637, 2024). "It is well-accepted that EZH2 catalyze H3K27me3 through interacting with DNMT1, DNMT3a and DNMT3b in cancer cells." (PMID 38992588, 2024). "We found that deleting the DNMT1 gene made cancer cells prone to increased TET2 expression and re-expression of p16 after drug treatment." (PMID 39057134, 2024). "The faithful maintenance of DNA methylation homeostasis indispensably requires DNA methyltransferase 1 (DNMT1) in cancer progression." (PMID 38755637, 2024). "Expression of DNMT1 often increases during cancer progression, including during the transition from PCa to NEPC." (PMID 40994652, 2024). "Among these genes, we can find some encoding cancer-relevant transcription factors such as E2F1 CTCF, and ERG and DNA methyltransferase enzymes (DNMT1)." (PMID 38773638, 2024). "This aberrant methylation is often accompanied by the overexpression of DNMT1 in various cancers, driven by cancer cell‐mediated signaling cascades." (PMID 38374872, 2024). "DNMT1 activity is perhaps even more important for the transcriptional stability of cancer cells undergoing continuous cell division cycles." (PMID 40994652, 2024). "When the top 1000 DMSs were assessed, sh-DNMT1 cancer cells exhibited complete DNA hypomethylation, and a few DMSs were distributed at CpG islands but at island shores." (PMID 38755637, 2024). "A crucial epigenetic modification in cancer development and progression is DNA methylation, which is modulated by the methyltransferase DNMT1." (PMID 39595939, 2024). "The study elucidated that EGCG attenuates DNMT activity and protein levels, encompassing DNMT1, DNMT3a, and DNMT3b, reinstates tumor suppressor genes, and diminishes cell proliferation, thereby offering a multifaceted approach to cancer treatment." (PMID 38879474, 2024). "DNMT1 is predominantly responsible for DNA methylation in cancer cells and plays a pivotal role in sustaining aberrant promoter methylation." (PMID 38303056, 2024). "In particular, the effect of DNMT1 status on the TET2 phenotype following DNMTi treatment remains elusive in cancer cells." (PMID 39057134, 2024). "This was evidenced by the reduction in phosphorylation levels of CDK1/2/3 and Rb proteins in sh-DNMT1 cancer cells." (PMID 38755637, 2024). "In NSCLC experimental models we have found that G9a/DNMT1 inhibition impairs cancer cell malignancy and reduces tumor growth, an effect that is mediated by enzymes AOX1 and SCARA5." (PMID 39488528, 2024). "Previous reports have shown that DNMT1, together with EZH2, contributes to the transcriptional repression of the miR-200 family members, and EZH2 depletion reduces DNMT1 presence on the miR-200b/a/429 promoter in cancer cells." (PMID 38890707, 2024).